IL10 (interleukin 10)
Diseases named in the same sentence as IL10 in open-access papers (continued):
Sharing a sentence is not in itself a finding about the gene and the disease.
brucellosis (continued). "It is also known that Th1 immune response characterized by IFN-γ and IL-12 secretion is important to control infection and that production of IL-10 has a negative impact in the course of brucellosis control by the host." (PMID 28018318, 2016). "Considering the negative impact of IL-10 on the establishment of a protective immune response during brucellosis, PG pathway could contribute to bacterial persistence." (PMID 28018318, 2016). "Though gene expression of the Th2 cytokine IL-10 was elevated in some brucellosis patients, IL-10 protein secretion was not significantly altered in these patients under any stimulation condition; IL-4, another important Th2 cytokine, was not highly secreted in any condition." (PMID 24040434, 2013). "It is also significant that the ability of macrophages to control intracellular B. abortus is affected by IL-10 only at very high concentrations, and that IL-6 and TNF-α have no major effect, in contrast to INF-γ which is the key cytokine in the control of brucellosis." (PMID 17637846, 2007). "Moreover, a 5-fold greater number of IL-10 producing CD4+CD25+ T cells was detected at 9 d.p.i., compared to IL-10 producing CD4+CD25− T cells, suggesting that the CD4+CD25+ T cell subset is the major population responsible for IL-10 production during acute brucellosis in the mouse." (PMID 23818855, 2013). "In the acute phase of brucellosis, infected patients exhibit higher levels of cytokines, such as TNF-α, IL-6 or IFN-γ, and IL-10, compared to Brucella-negative individuals." (PMID 38139181, 2023). "However increased IL-10 gene expression after stimulation with HKBM in both acute and relapse brucellosis patients, but not after LPS stimulation, may suggest a possible Brucella spp." (PMID 24040434, 2013).
esophageal cancer (19 papers, 2014 to 2025). A primary or metastatic malignant neoplasm involving the esophagus. "Mediating effects of IL-10 on the causal relationship between 2 immune cell phenotypes and esophageal cancer." (PMID 39496002, 2024). "In a Chinese study, IL10 rs1800872 was associated with an increased risk of esophageal cancer." (PMID 36233401, 2022). "Also, IL-10 rs1800872 T>G polymorphism was associated with an increased risk of esophageal cancer in a Chinese population." (PMID 33953642, 2021). "The correlation between IgG4 and IL-10 in the serum of esophageal cancer patients, revealing a positive correlation (R=0.4030, P<0.01) compared to healthy controls." (PMID 39896813, 2024). "The levels of IgG4 (P<0.01, **) and IL-10 (P<0.0001, ****) in the serum of esophageal cancer patients were significantly elevated compared to those in healthy controls." (PMID 39896813, 2024). "IL-10+ Breg frequency also correlated with clinical staging and disease progression in esophageal cancer patients, as higher frequencies were seen in the peripheral blood of patients with Stage III/IV disease compared to early stage disease patients." (PMID 27437104, 2016). "In patients with esophageal cancer, frequencies of peripheral blood IL-10+ Bregs were significantly greater compared with healthy controls." (PMID 27437104, 2016). "A higher frequency of IL-10-producing B cells was observed in late-stage esophageal cancer samples compared to early-stage samples, suggesting that Breg cells play a role in the progression of esophageal cancer." (PMID 40160817, 2025). "This could be attributed to the inflammatory responses present in esophageal cancer patients, which stimulate the production of IgG4 and IL-10." (PMID 39896813, 2024). "IgG4 and IL-10 may contribute to immunosuppression in esophageal cancer by promoting the polarization of M2 macrophages within TLS, which could be a therapeutic target." (PMID 39896813, 2024). "The increased levels of IgG4 and IL-10 in esophageal cancer patients may be due to the inflammatory response and the subsequent increase in leukocytes within the body." (PMID 39896813, 2024). "IL-10 is not reported to be related to esophageal cancer in the public database and GCNLMF predicted it as an esophageal cancer-related gene." (PMID 36052230, 2022).
head and neck cancer (19 papers, 2002 to 2025). A primary or metastatic malignant neoplasm affecting the head and neck. "Makni and co-authors analyzed the IL-10 polymorphisms’ susceptibility to head and neck cancers (HNC)." (PMID 36009467, 2022). "We investigated the association of three IL-10 promoter single-nucleotide polymorphisms and altered IL-10 plasma levels with the risk of head and neck cancer (HNC)." (PMID 30762321, 2019). "The association of interleukin-10 rs1800896 polymorphism with head and neck cancer risk and its clinical stages has been investigated by many published studies, but the results remain inconsistent." (PMID 28410223, 2017). "Molecular analyses of head and neck cancer tumors that progressed despite treatment, identified IL-10 and integrin pathways to be strongly associated with cancer progression." (PMID 26747525, 2016). "Several studies have suggested that patients with advanced head and neck cancer have elevated serum levels of IL-10 and this finding is associated with poor prognosis." (PMID 25153698, 2014). "Molecular epidemiological research suggests that interleukin-10 (IL-10) polymorphisms may be associated with an increased risk of head and neck cancer (HNC), but results remain controversial." (PMID 26612133, 2015). "Mean value levels (ng/ml) of Interleukin 1-beta (IL-1β), Interleukin 6 (IL-6), and Interleukin 10 (IL-10) before treatment, 7 weeks after the start of treatment, 3 and 12 months after the termination of treatment in patients with head and neck cancer." (PMID 31750257, 2019). "As Th1 responses are favorable for controlling head and neck cancer, production of the immunosuppressive cytokine, IL-10, suppresses the Th1 response and favors the Th2 response, promoting the growth of head and neck cancer." (PMID 24348811, 2014). "Similarly, IL-10 was shown to be upregulated in head and neck cancer and correlated with tumor progression via the JAK-STAT system, also inducing the expression of IL-6." (PMID 36143043, 2022). "We concluded that interleukin-10 rs1800896 polymorphism was significantly associated with head and neck cancer risk but not with the clinical stages thereof." (PMID 28410223, 2017). "The head and neck cancer patients’ salivary cytokines that were assessed by the studies, along with photobiomodulation therapy, included IL-12p70, TNF-α, IL-6, IL-8, IL-10, CXCL8, and IL-1β." (PMID 38792366, 2024). "The outliers of IL-6, IL-10 and TNF in the post-index group were detected in saliva samples from different patients with head and neck carcinoma, and all sampling time was at OM occurrence." (PMID 35476641, 2022). "Significant differences in the circulating levels of serum IL-6, IL-8, IL-10, MCP-1 and IP-10 after three months of the nutritional intervention were observed in patients with head and neck cancer, neuroendocrine tumors, gastric, colon, urothelial or other types of cancer." (PMID 38892006, 2024). "Indeed, the other researchers had assessed the presence of salivary cytokines (e.g., IFN-γ, IL-1β, IL-6, IL-8, IL-10, TNF-α, VEGF) in patients with head and neck cancer (HNC)." (PMID 29515773, 2018). "Perhaps the lack of TGF-β and IL-10 is not too surprising as others have demonstrated that in head and neck cancers, Tregs that primarily secrete IL-10 and TGF-β are those within the population of tumor infiltrating lymphocytes and are not those in circulation." (PMID 25153698, 2014).
hepatitis C (19 papers, 2009 to 2024). "Several biomarkers have been shown to predict clinical acute rejection, including primary biliary cirrhosis, younger age, hepatitis C, IL-10-1082 polymorphism, de novo donor-specific antibody, and cytokine promoter polymorphisms." (PMID 33933100, 2021). "Another research studying the IL-10 genotype and hepatitis C also shows strong association of different promoter haplotypes with degrees of IL-10 production." (PMID 30873205, 2019). "The G allele for IL-10 (−1082 A/G), the C allele for IL-4 (+3 C/T) and the C and T alleles for IL-28B (rs12979860 and rs8099917, respectively) are associated with spontaneous viral clearance in hepatitis C infection." (PMID 22986179, 2012). "For example, blocking TIM-3 followed by TLR agonist treatment resulted in the expression of IL-12, interleukin-10 (IL-10), and interleukin-6 (IL-6) in hepatitis C monocytes, and this strategy may be applicable to cancer." (PMID 32087708, 2020). "Likewise, for module 2 type II interferon signaling (IFNG), IL-10 anti-inflammatory signaling pathway, influenza A, pertussis, hepatitis C, toll-like receptor signaling pathway and RIG-I-like receptor signaling were enriched." (PMID 32785106, 2020). "Similarly, in our current analysis, we found that among hepatitis C monoinfected subjects, those with detectable TF had a trend toward lower IL-10 levels." (PMID 25884329, 2015). "Interestingly, in two reported trials on hepatitis C, treatment with IL-10 has already been shown to result in normalization of aminotransferase levels, improved liver histology and reduced fibrosis." (PMID 25147572, 2014). "Raised AST levels during acute liver damage, has been associated with secreted IL-1ra which is an acute phase protein produced by liver cells and also with IL-10, an anti-inflammatory cytokine which have previously correlated to necroinflammatory activity in liver damaged hepatitis C patients." (PMID 23284941, 2012). "Whilst IL-10 does appear to play a role in immune suppression in pigs during infection with FMDV, it is most commonly associated with the maintenance of chronic infections such as Hepatitis C in humans and Mycobacterium Bovis in cattle." (PMID 22014145, 2011). "Increased IL-10 production by APCs is also observed during HIV and hepatitis virus C infections and has been shown to specifically down-regulate T-cell responses." (PMID 19478852, 2009). "IL-10 may be used to regulate the immune response during certain infectious diseases, such as HIV infection and hepatitis C. While an effective immune response is crucial for clearing infections, an overly aggressive response can lead to tissue damage." (PMID 38248028, 2024).
Hyperinsulinemia (19 papers, 2010 to 2024). An increased concentration of insulin in the blood. "The present study showed that the HF diet induced an increase of TNF-α and IL-6 pro-inflammatory cytokines plasma level and a decrease of IL-4 and IL-10 anti-inflammatory cytokines plasma level, associated with hyperinsulinemia and a high HOMA-IR index." (PMID 31091691, 2019). "Here, we show how hyperinsulinemia shapes CD4+ T cell attainment by reducing the production of IL-10 and causing a shift towards pro-inflammatory, resting, or TGFβ + producing cell types." (PMID 28651594, 2017). "Serum IL-10 has a converse relationship with hyperinsulinemia and IR, as IL-10 decreases with HOMA-IR increased." (PMID 34099024, 2021). "The two nodes whose transitions in response to transient perturbations varied more among environments (i.e., basal insulin versus hyperinsulinemia) were IL10 and, trivially, INSULIN itself." (PMID 28651594, 2017). "Compared to a reference bottlenose dolphin without metabolic perturbations, the current study identified activated cytokine gene expression, including TGF-β, TNF-α, IFN-γ, IL-18, IL-13, IL-10, and IL-4 in the liver or spleen of a geriatric bottlenose dolphin with hyperinsulinemia." (PMID 24101915, 2013). "To simulate the effect of hyperinsulinemia we extended the previous network to add the regulation of IL-10 by insulin via the AKT pathway; and the STAT3-signaling cytokines: IL-10, IL-6, and IL-21 all use STAT3." (PMID 28651594, 2017). "Hyperinsulinemia can decrease ACTH secretion and, together with chronic exposure to IL-10, TGF-β1 and TNFα could also decrease cortisol secretion." (PMID 37718435, 2023). "Due to the pro-inflammatory nature of hyperinsulinemia, it is not surprising that corresponding anti-inflammatory cytokines, IL-4, IL-10, IL-13, and TGF-β, would also be upregulated in an effort to control the inflammation." (PMID 24101915, 2013). "Rosiglitazone treatment reduced hyperinsulinemia (DIO 4510 +/− 490 pg/ml: DIO-Rosi 2170 +/− 620 pg/ml), serum CCL2 levels (DIO 84.2 +/− 0.18 pg/ml: DIO-Rosi 47.3 +/− 4.6 pg/ml) and SVF mediator production of IL-6, TNFα, IL-1β and IL-10." (PMID 20445733, 2010). "In the current study, we demonstrate inhibitory effects of exogenous IL-10 systemic administration on pain behaviors and skin inflammatory cell aggregation without affecting IGT, IFG, hypercholesterolemia, and hyperinsulinemia." (PMID 29408929, 2018). "In our study, 8-week HF feeding to mice induced mild body weight gain (14.4% or 3.7 g), increased FBG level within the normal range (< 126 mg/dL), and upregulated levels of a part of serum cytokines (TNF-α and IL-10) and lipids (TC and HDLC) without hyperinsulinemia." (PMID 30719451, 2019).
infarction (19 papers, 2015 to 2025). A localised pathological necrosis of tissue resulting from obstruction of the blood supply usually by a thrombus, an embolus, or vascular torsion. "Interleukin 10 is a key anti-inflammatory cytokine with recognized effects on immune and non-immune cells and has been implicated in the regulation of post-infarction inflammatory response." (PMID 29123530, 2017). "IL-10 can improve left ventricular function, reduce infarction size, and mitigate infarct wall thinning." (PMID 39200761, 2024). "In this setting, IL-10 has been shown to decrease IS, necrosis and fibrosis and improve LV function and remodeling in mice after infarction, and also reduce the incidence of HF progression after angioplasty in patients." (PMID 37104236, 2023). "In an animal model, cerebral infarct volume have been reduced through intraventricular or systemic administration of IL-10, and IL-10 has been suggested to be neuroprotective." (PMID 31164999, 2019). "The baseline serum level of IL-10 ≥ 14.5 pg/ ml and size of infarct area > 3.5 cm3 were found to be the independent predictors of PSI." (PMID 27453748, 2016). "Therefore, this research aims to analyze the effects of colchicine on reducing excessive inflammation postmyocardial infarction through IL-10 using both in silico and in vitro studies." (PMID 39200761, 2024). "Regarding the role of the NF-kB signalling pathway, we hypothesized that its participation in the pathogenesis of AMI may also be related to CD4-expressing T cells, TNF-α and IL-10 in myocardial ischaemia and infarction." (PMID 32332808, 2020). "In addition to the reduced expression of proinflammatory cytokines, statins also improve the balance between TNF-α and IL-10 in postmyocardial infarction in rats." (PMID 30524484, 2018). "Similarly, a 6‐month RCT in diabetic patients 48 and an 8‐week RCT in postmyocardial infarction patients 44 showed moderate‐aerobic exercise increased IL‐10 levels compared to control groups." (PMID 27485297, 2016). "Neither acute nor chronic phase IL-10 plasma concentrations were associated with prior or recent (<6 months) ischemic MI, vertebral/carotid stenosis, given intravenous thrombolytic treatment, or infarction volume in cerebral tissue." (PMID 25923658, 2015). "Several studies have demonstrated that BXT can reduce infarction size, myeloperoxidase, IL-6, and CRP while increasing SOD and anti-inflammatory mediators such as interleukin 10 (IL-10)." (PMID 35387325, 2022). "The data suggested that BXT could decrease the infarction size, myeloperoxidase, interleukin-6 (IL-6), and levels of C-reactive protein (CRP) and enhance SOD activities and anti-inflammatory media such as interleukin-10 (IL-10)." (PMID 30918578, 2019).
intracerebral hemorrhage (19 papers, 2014 to 2026). A cerebrovascular disorder characterized by bleeding into one or both cerebral hemispheres including the basal ganglia and the cerebral cortex. "Mice deficient in IL-10 demonstrate greater pathological injury following intracerebral hemorrhage, characterized by heightened brain edema and damage to white matter." (PMID 39881806, 2024). "Therapeutic assessments revealed significant improvements in recovery, accelerated hematoma clearance, and reduced inflammation, highlighting the potential of IL-10-loaded nanoparticles for the targeted treatment of intracerebral hemorrhage." (PMID 40557148, 2025). "For example, IL-10 was conjugated onto phosphatidylserine liposomes for targeted delivery to microglia and macrophages in intracerebral hemorrhage, a severe form of stroke." (PMID 40557148, 2025). "Weak indirect evidence supporting the protective role of IL-10 in preclinical models of intracerebral hemorrhage exists; however, in the limited number of clinical studies, higher IL-10 levels seen post-ictus have been associated with worse outcomes." (PMID 28659854, 2017). "More recently, in vivo, IL-10 originated from regulatory T cells was shown to mediate microglia polarization towards the M2 phenotype ameliorating the outcome of intracerebral haemorrhage." (PMID 27881137, 2016). "Similarly, regulatory T cells (Tregs) have been reported to alleviate inflammatory injury after intracerebral hemorrhage by shifting the microglia/macrophage polarization toward the M2 phenotype via the IL-10/GSK3B/PTEN axis." (PMID 41476593, 2025). "Likewise, IL-10 from Tregs modulates the alternative (M2) microglial polarization to ameliorate the outcome of intracerebral hemorrhage." (PMID 35844606, 2022). "Summary of IL-10 intracerebral hemorrhage preclinical studies." (PMID 28659854, 2017). "During the recovery phase following intracerebral hemorrhage, the levels of IL-10 may further rise." (PMID 39881806, 2024). "A study has found that the expression of IL‐10 did not change significantly in the autogenous blood intracerebral hemorrhage model." (PMID 37614117, 2023). "In this sense, it has been reported that endothelial progenitor cells improved the neurological function of rats with intracerebral hemorrhage by decreasing pro-inflammatory cytokines such as IFN-γ, IL-6, and TNFα, and increasing anti-inflammatory cytokines such as TGFβ1 and IL-10." (PMID 29720269, 2018).